RNU6-975P (RNA, U6 small nuclear 975, pseudogene)
Gene: Small nuclear RNA gene on chromosome 6 (73,464,073 to 73,464,177, forward strand). Ensembl gene ENSG00000207023.
Homologues: Orthologues: chimpanzee U6 (100% identical), macaque U6 (88% identical), dog U6 (76% identical), guinea pig U6 (67% identical), mouse Gm55959 (59% identical). Paralogues in human: RNU6-480P (90% identical), RNU6-16P (88% identical), RNU6-144P (87% identical), RNU6-333P (87% identical), RNU6-80P (87% identical), RNU6-21P (86% identical), RNU6-356P (86% identical), RNU6-46P (86% identical), RNU6-940P (86% identical), RNU6-1 (85% identical), RNU6-1005P (85% identical), RNU6-1181P (85% identical), and 1289 more.